ITGB3 (integrin subunit beta 3)
Diseases named in the same sentence as ITGB3 in open-access papers (continued):
Sharing a sentence is not in itself a finding about the gene and the disease.
melanoma (continued). "The expression of ITGB3 was restricted exclusively to cells within vertical growth phase and metastatic melanomas and was correlated with shorter survival." (PMID 27833078, 2016). "Several of the EMT-related genes with higher expression in NR patients encoded for molecules controlling adhesion (ITGB3, VCAM1, collagens, and others), interaction with extracellular matrix (VEGFA, MMP14, WNT5A, LAMA1, and others), and melanoma de-differentiation (KRT9, KRT10, EGFR, and others)." (PMID 37739939, 2023). "Interestingly, one of the most important proteins associated with melanoma potential is ITGB3/CD61, and CD90 and CD51/CD61 have already been shown to functionally interact in melanoma cell adhesion." (PMID 35727432, 2022). "As previously reported, ADAR1 could mediate melanoma invasion and metastasis via controlling ITGB3 expression." (PMID 35003354, 2021). "Indeed, statistically significant downregulation of ADAR1 and FoxD1, as well as upregulation of ITGB3, were observed congruently along human melanoma progression." (PMID 29855470, 2018). "Here we show that ADAR1 silencing enhances melanoma cell invasiveness and ITGB3 expression." (PMID 29855470, 2018). "Importantly, the expression of ADAR1 and FOXD1 decreased, while the expression of ITGB3 increased, along melanoma development." (PMID 29855470, 2018). "Moreover, the reduced ITGB3 expression and invasion function conferred by ITGB3-specific KD with siRNA were restored by treatment with anti-miR-22, as demonstrated in all four melanoma lines." (PMID 29855470, 2018). "Moreover, when comparing integrin gene expression in melanoma tissues with distinct Breslow thickness, a significantly higher ITGB3 expression was observed in thicker tissue samples (2–4 mm and > 4 mm) compared to tissues with lower Breslow thickness (<2 mm) (p = 0.004)." (PMID 36091936, 2022). "In addition, ITGB3 was vital in the progression and invasion of melanoma." (PMID 30780128, 2019). "Thus, abnormal expression of ITGB3 in melanoma may serve as a prognostic marker." (PMID 39796775, 2025). "It prompted the genes ITGA4, SPP1, and ITGB3 to promote the interactions between melanoma cells and the ECM and thus facilitated melanoma metastasis." (PMID 35054979, 2022). "Inhibition of ITGB3-SRC-STAT3 pathway activation can sensitize tumor-repopulating cells to the effects of IFN-α, and enhance the overall efficacy of melanoma treatment." (PMID 34660316, 2021). "When let7a expression is lost or decreased, ITGB3 and NRAS expression boosts and promotes the melanoma invasive phenotype." (PMID 29112174, 2017). "At the protein level, FN1, ITGB3, and NFATC2 were expressed in a manner similar to CTHRC1 in our panel of melanoma cell lines." (PMID 26918341, 2016). "Interestingly, the genes coordinately expressed with CTHRC1, i.e. ITGB3, NFAT, and FN1, have all been implicated in angiogenesis, suggesting that these molecules may be associated with the increased angiogenesis and blood vessel density detected in melanomas." (PMID 26918341, 2016). "Other genes correlating with CTHRC1 expression in melanoma cell lines included the transcription factor NFATC2 and ITGB3." (PMID 26918341, 2016). "In contrast, in tumor-repopulating melanoma cells, ITGB3 confers resistance to interferon-α-induced apoptosis by suppressing retinoic acid-inducible gene-I (RIG-I), indicating the involvement of ITGB3 in the anti-apoptotic process." (PMID 38814534, 2024). "Transcription of ITGB3 gene induces the expression of NME1, a metastatic suppressor, in melanoma." (PMID 34660316, 2021). "Importantly, the enhanced ITGB3 expression and invasive function following ADAR1-KD were restored by overexpression of miR-22 in the same cells, as demonstrated in all four melanoma lines." (PMID 29855470, 2018).
melanoma (continued). "ITGB3 has been suggested to play an important role in melanoma progression since it is overexpressed in VGP primary melanomas and in melanoma metastases, and its overexpression induces the conversion of melanoma cells from the radial to vertical growth phase." (PMID 26918341, 2016). "Congruently, exploration of scRNA-seq data (via Single Cell Portal) revealed that elevated levels of ITGAV, ITGB3 and ITGB5 in myeloid cells are negative predictors of ICI therapy response in melanoma and renal cell carcinoma patients." (PMID 40281508, 2025).
Glanzmann thrombasthenia (31 papers, 2013 to 2026). "This is particularly pertinent given the observed association in populations with β3-deficient Glanzmann’s Thrombasthenia, suggesting a broader and more complex influence of ITGB3 on cardiovascular health." (PMID 39028281, 2024). "Glanzmann thrombasthenia (GT) is an autosomal recessive platelet functional bleeding disorder caused by mutations in the ITGA2B or ITGB3 genes, often presenting as mucocutaneous bleeding." (PMID 39776701, 2024). "Glanzmann thrombasthenia is caused by mutations in either the GP2B (ITGA2B) or GP3A (ITGB3) gene, and at least 100 mutations have been described and collected in an online database." (PMID 33274150, 2020). "Mutations of Itga2b and Itgb3 are assoicated with Glanzmann thrombasthenia, the most common inherited disease of platelet function in humans, causing a bleeding disorder." (PMID 24147020, 2013). "Mutations in ITGA2B and ITGB3 cause Glanzmann thrombasthenia, an inherited bleeding disorder in which platelets fail to aggregate when stimulated." (PMID 24236036, 2013). "The homozygous mutations in ITGA2B or ITGB3 locus could cause Glanzmann thrombasthenia, a bleeding disorder." (PMID 34837956, 2021). "Encoded by the genes ITGA2B and ITGB3, mutations are associated with Glanzmann thrombasthenia (GT)." (PMID 27025194, 2016). "Glanzmann thrombasthenia (GT) is a rare, autosomal recessive platelet aggregation disorder caused by mutations in the ITGA2B and ITGB3 genes." (PMID 41798562, 2026). "Glanzmann’s thrombasthenia, the most representative IPFD, results from ITGA2B or ITGB3 mutations that disrupt the αIIbβ3 integrin complex, producing severe mucocutaneous bleeding." (PMID 41301446, 2025). "For instance, in Glanzmann thrombasthenia, an autosomal recessive genetic disease, asymptomatic carriers who are heterozygous for the causative gene (ITGA2B or ITGB3) tend to have a lower expression of integrin glycoprotein IIb-IIIa on the platelet surface than those in the control group." (PMID 40022154, 2025). "Moreover, ITGB3 also participates in several blood-related diseases including Glanzmann Thrombasthenia as well as bleeding disorder." (PMID 34738870, 2021). "Itgb3-null mice fail to express the widely expressed αvβ3 integrins and the platelet-specific αIIbβ3 integrin, and suffer from a bleeding disorder resembling human Glanzmann thrombasthenia." (PMID 28092265, 2017). "Glanzmann thrombasthenia (GT) is an autosomal recessive platelet disorder caused by mutations in the ITGA2B or ITGB3 genes encoding the plasma membrane glycoproteins αIIb (GPIIb, CD41) and β3 (GPIIIa, CD61), respectively." (PMID 25607928, 2015).
Stroke (21 papers, 2009 to 2025). Sudden impairment of blood flow to a part of the brain due to occlusion or rupture of an artery to the brain. "The investigations revealed that the mutant genotype of the rs5918 polymorphism in the ITGB3 gene has a risk of thrombosis formation with increased levels of platelet activation, which is common for coronary artery diseases, stroke, and myocardial infarction." (PMID 38068287, 2023). "There are reports that mutant CC genotype of rs5918 in the ITGB3 gene has higher risk of thrombosis formation in cases of stroke, coronary artery disease and myocardial infarction (MI)." (PMID 35629166, 2022). "Within the specific stroke causes, only nine genes were represented by 23 exons and junctions that were common between the sexes, yet only one, ITGB3, showed exons/junctions with similar expression patterns in both sexes." (PMID 33193047, 2020). "In both male and female stroke brains, we found that MMP-3 KO decreased the expression of Itga10 and Itgb3, which encode the subunits that form integrin αvβ3." (PMID 39000490, 2024). "ITGB3 is a key gene involved in the development of COVID-19-related stroke, in line with our findings." (PMID 37090981, 2023). "At gene level, few were differentially expressed: ALDH2, ALOX5AP, F13A1, and IMPA2 (males, all stroke); ITGB3 (females, cardioembolic); ADD1 (males, atherosclerotic); F13A1, IMPA2 (males, lacunar); and WNK1 (females, lacunar)." (PMID 33193047, 2020). "The platelet proteomic profiling data revealed that the differences in log2 ratio intensities between ITGA2B and ITGB3 levels of stroke patients and of those patients in the control group." (PMID 27336623, 2016). "The CytoHubba plug-in of the Cytoscape was utilized to visualize the genes of stroke-related crucial module, and the top five genes were selected as hub genes using EcCentricity as the ranking method (MPO, MMP9, ITGA2B, ITGB3, and RETN)." (PMID 35557984, 2022). "Similarly, genes involved in integrin cell surface interactions including Itga10, Itgb3, Vcam1, Itgb1, Itgae, Itgb7, Itga1, Itga5, Icam1, Itgb2, Pecam1, and Icam2 were depleted in male MMP-3 KO stroke brains." (PMID 39000490, 2024).
ovarian carcinoma (18 papers, 2005 to 2024). A malignant neoplasm originating from the surface ovarian epithelium. "Another miRNA, miR-506, has been shown to inhibit ovarian cancer progression by directly targeting the integrins ITGA6 and ITGB3, both of which are implicated in ovarian cancer cell migration, invasion, and survival." (PMID 37760437, 2023). "The best characterised example of nuclear integrins is ITGAV/ITGB3 in ovarian cancer; in this case, nuclear localisation was cancer-specific, and induced proliferation without interfering with the adherence function of the plasma-membrane located fraction." (PMID 34253873, 2021). "Given that PRKCZ expression correlates with the expression of both IGF1R and ITGB3, we further examined if alteration of these genes can affect the migration phenotype of ovarian cancer cells that over-express PRKCZ." (PMID 25874946, 2015). "Lastly, to evaluate if ITGB3 plays a role in ovarian cancer migration, scratch wound healing assays were performed with SKOV3 cells treated with ITGB3 siRNA." (PMID 25874946, 2015). "Interestingly, our assessment of ITGB3 expression in PRKCZ-expressing SKOV3 and OVCAR3 ovarian cancer cells showed that ITGB3 is down-regulated in the presence of PRKCZ, as its gene and protein expressions were both decreased compared to controls." (PMID 25874946, 2015). "Transcription of TIMP1 (TIMP metallopeptidase inhibitor 1) has previously been shown to be up-regulated by ITGB3 in the ovarian cancer cell line MDAH 2774 and thus may be a candidate target." (PMID 25874946, 2015). "Nevertheless, results from this study suggest one possible mechanism by which ITGB3 expression may be altered, and as a consequence, a more aggressive phenotype of ovarian cancer cells is developed." (PMID 25874946, 2015). "The expression of ITGB3 in the normal ovarian epithelium and its expression in well-differentiated ovarian carcinomas may reflect the preservation of normal cell properties." (PMID 19775429, 2009). "Among all analyzed integrin genes, we found increased ITGA3/A5/A10/A2B and ITGB3/B4/B8 expressions were significantly associated with poor OS, while decreased ITGA6/A7/AE and ITGB7 expression were significantly associated with poor OS in ovarian cancer patients." (PMID 32765584, 2020). "Hence, we asked whether following PAX8 inhibition ITGB3 expression was modified also in normal Fallopian tube and in general in ovarian cancer cells." (PMID 31832016, 2019). "The mRNA levels of ITGA1, ITGB1, ITGB3, and ITGB8 were found to be highly elevated in ovarian cancer tissues compared to those in normal ovarian tissues." (PMID 37596406, 2023). "In ovarian cancer cells, overexpression of miR-506 significantly decreased ITGA6 and ITGB3 expression and led to reduced cell migration and invasion." (PMID 37760437, 2023). "In particular, we found PI3K-Akt initiators; such as the RTKs EGFR1 and VEGFA, and the integrins ITGB3 and ITGB6, to be potential drug targets in ovarian cancer patients with high CTCFL expression." (PMID 35132075, 2022). "Further, ITGB3 protein expression have been detected in normal ovarian epithelium and highly differentiated ovarian carcinomas, but are lacking in most of the less-differentiated tumours." (PMID 19775429, 2009). "Our data further illustrate that up-regulation of PRKCZ leads to expression alterations of IGF1R and ITGB3 in SKOV3 and OVCAR3 cell lines, suggesting that PRKCZ may participate in ovarian cancer progression by modulating the expression of other important signalling molecules." (PMID 25874946, 2015). "Based on our observations that both ITGB3 mRNA and protein levels are decreased in PRKCZ-expressing cells in two ovarian cancer cell lines (SKOV3 and OVCAR3), we sought to identify potential downstream players within this signalling pathway that may play role in ovarian cancer." (PMID 25874946, 2015).
ovarian carcinoma (continued). "We observed in this independent set of samples that FOLR1, ITGB3, ITGA5 and ACSL4 have higher expression for majority of the ovarian cancer cases compared to the non-ovarian cases." (PMID 37884576, 2023).
glioma (16 papers, 2012 to 2025). A benign or malignant brain and spinal cord tumor that arises from glial cells (astrocytes, oligodendrocytes, ependymal cells). "It has been previously shown that a significant downregulation of ITGB3 was associated with BCNU-resistance in C6 glioma cells." (PMID 22942880, 2012). "It was showed that ITGA5 and ITGB3 are expressed in glioma vessels and tumor cells and the gene expression is significantly associated with the malignancy grade of the tumor and poor patient prognosis." (PMID 33036421, 2020). "Some genes in this survival module were similarly implicated in the occurrence and development of glioma, such as ERBB2, ITGB3, EGFR, and MET." (PMID 24809850, 2014). "We found a link between let-7i and integrin β3 (ITGB3) whose pro-apoptotic role has been reported in glioma cells." (PMID 23358700, 2013). "Among numerous proteins that were up- or down-regulated in drug-resistant glioma cells, lipocalin 2 (LCN2) and integrin β3 (ITGB3) were identified as key proteins that determine the survival and death of glioma cells." (PMID 22942880, 2012). "Among numerous proteins identified by the proteomic comparison of drug-sensitive and resistant glioma cells, lipocalin 2 (LCN2) and integrin β3 (ITGB3) played a central role in regulating glioma chemosensitivity." (PMID 22942880, 2012). "There was a positive correlation between the ITGB3 expression level and the chemosensitivity to anticancer drugs in human glioma cells." (PMID 22942880, 2012). "Expression of LCN2, ITGB3, and other specific proteins should also be evaluated in glioma tissues of the patients in future studies." (PMID 22942880, 2012). "Taken collectively, previous studies provide the evidence for the pro-apoptotic role of LCN2 and ITGB3 in glioma cells." (PMID 22942880, 2012). "ITGB3 was another protein whose expression was significantly down-regulated in the BCNU-resistant C6 glioma cells." (PMID 22942880, 2012). "By analyzing publicly accessible scRNA-seq data from human gliomas via the SingleCell portal, we detected the predominant expression of ITGAV, ITGB3 and ITGB5 (encoding αv, β3 and β5 integrins, respectively) in clusters of myeloid cells, pericytes and endothelial cells." (PMID 40281508, 2025). "Furthermore, they found that the knockdown of MFG-E8 inhibits glioma cell growth via the ITGB3/FAK/ERK or ITGB3/STAT3/cyclin D3 signaling pathways and suppresses M2 polarization." (PMID 37759870, 2023). "LCN2 and ITGB3 could be exploited to develop a new therapeutic approach to sensitizing glioma to anticancer drugs." (PMID 22942880, 2012). "LCN2, ITGB3, and other proteins identified by proteomic analysis of glioma chemoresistance may help overcome drug resistance of glioma and improve clinical outcomes of patients." (PMID 22942880, 2012). "LCN2, ITGB3, and other proteins identified by proteomic analysis could be utilized to overcome glioma chemoresistance." (PMID 22942880, 2012). "Pharmacological and biochemical studies indicated pro-apoptotic functions of ITGB3 in glioma cells, which may be mediated by Erk activation and the unligated integrin-mediated cell death (IMD) pathway." (PMID 22942880, 2012). "Moreover, nitric oxide (NO) enhanced anticancer drug-induced glioma cell death by increasing ITGB3 expression." (PMID 22942880, 2012). "Survival analysis based on the expression of individual integrin genes or a multigene signature revealed that high levels of ITGAV, ITGB3 and ITGB5 correlate with a poor prognosis in glioma patients." (PMID 40281508, 2025). "ITGB3 and ITGB5 have been reported to modulate apoptosis and proliferation in glioma cells, contributing to tumour progression." (PMID 41009755, 2025). "In addition to the induction of ITGB3, we observed that TWEAK treatment also elevated the expression of ITGA11, which has previously been described in glioma invasion." (PMID 36945490, 2023).
glioma (continued). "Furthermore, although not correlating to response to irradiation, recent studies have shown that COL1A1, ITGA7, ITGB3, ITGB4, HMMR and IBSP upregulation confer low survival rate to glioma patients." (PMID 34211843, 2021). "The quantitative real-time PCR method was used to evaluate mRNA expression of SEMA3(A-G), neuropilins (NRP1 and NRP2), plexins (PLXNA2 and PLXND1), cadherins (CDH1 and CDH2), integrins (ITGB1, ITGB3, ITGA5, and ITGAV), VEGFA and KDR genes in 59 II-IV grade glioma tissues." (PMID 33036421, 2020). "Last, ITGB3, an integrin component that is known to be down-regulated in drug-resistant gliomas, was undetected in two of three non-responders." (PMID 28345020, 2017).